HIF1A (hypoxia inducible factor 1 subunit alpha)
Diseases named in the same sentence as HIF1A in open-access papers (continued):
Sharing a sentence is not in itself a finding about the gene and the disease.
endometrial cancer (continued). "P13K/mTOR pathway inhibitors can sensitize endometrial cancer to radiation therapy by inhibiting HIF-1a/VEGF signaling." (PMID 30935077, 2019). "EGCG exhibits strong hypomethylating potential and also inhibits tumor angiogenesis in xenograft models through down-regulation of vascular endothelial growth factor A (VEGFA) and hypoxia inducible factor 1 alpha (HIF1α) in endometrial cancer." (PMID 30103412, 2018). "In endometrial cancer cell lines inhibition of the PI3K pathway is demonstrated to sensitize cancer cells to radiotherapy through down regulation of HIF-1α." (PMID 27634881, 2016). "In this study, we observed that TM treatment clearly inhibits the activity of complex IV in the ovarian and endometrial cancer cells used in our study, which also correlated with a reduction in HIF-1α levels." (PMID 26469226, 2015). "Using ovarian and endometrial cancer cell lines, we observed that TM downregulates HIF-1α protein levels and HIF-transcriptional targets involved in tumor angiogenesis and glycolysis, but did not affect HIF-1α protein synthesis." (PMID 26469226, 2015). "HIF-1α is involved in the progression of endometrial cancer through the regulation of p27kip cell cycle inhibitor." (PMID 24745019, 2014). "In previous study, we showed SHARP1 suppresses angiogenesis of endometrial cancer by decreasing HIF-1α level." (PMID 24997474, 2014). "Statistical analyses revealed significant differences between the HIF-1α expression and Bokhman subtypes of endometrial cancer (P = 0.0115)." (PMID 24745019, 2014). "The results of previous studies on the prognostic value of HIF-1α in endometrial cancer are inconclusive and controversial." (PMID 24745019, 2014). "Due to high prevalence of PTEN mutations and resultant activation of PI3K/AKT pathway, stabilization of HIF-1α and activation of various target genes are frequently observed in endometrial cancer cells." (PMID 24745019, 2014). "The increase in the expression of HIF-1α is accompanied by an increase in vascular density, a marker of angiogenesis; this points to the relationship between HIF-1α, angiogenesis, and endometrial cancer." (PMID 24745019, 2014). "Different (indirect) HIF-1α inhibitors that are in clinical trial for the treatment of advanced/recurrent endometrial carcinoma are Topotecan, Rapamycin derivates, and Bevacizumab." (PMID 20169098, 2010). "Contradictory results have been described as to the prognostic value of HIF-1α overexpression in endometrial carcinoma." (PMID 20169098, 2010). "In endometrial cancer, the interaction between HIF-1α and MST2 may bypass the canonical YAP/TAZ axis, directly coupling to the apoptotic machinery." (PMID 41256331, 2025). "Similarly, in endometrial cancer Ishikawa cells, hypoxic stress not only induces apoptosis via HIF-1α but also promotes Caspase-dependent cleavage of MST2, a process significantly inhibited by the pan-caspase inhibitor Z-VAD-FMK." (PMID 41256331, 2025). "Importantly, hierarchical pathway analysis identified PI3K/AKT signaling as a canonical upstream regulator that modulates the stability and activity of HIF-1α through phosphorylation in disease models such as endometrial cancer, and asthma." (PMID 40944191, 2025). "Since VEGF is a critical downstream effector of hypoxia-driven HIF-1α activation and a key driver of neovascularization in endometrial cancer, its marked reduction suggests that BA and GEM may impair the vascular supply essential for tumor growth and survival." (PMID 41470183, 2025). "The ECC-1 line was chosen because it represents a well-differentiated, estrogen-responsive endometrial carcinoma subtype that stably expresses key apoptotic and angiogenic markers such as HIF-1α, VEGF, Bax, and Bcl-2, making it an appropriate model for hypoxia-related investigations." (PMID 41470183, 2025). "Menin expression was highly correlated with HIF1A expression in human endometrial cancer samples." (PMID 39336822, 2024).
endometrial cancer (continued). "Another study observed that exosomal miR-320a, derived from CAFs, has lower expression in endometrial cancer cells and tissues: it targets hypoxia-inducible factor 1 subunit alpha (HIF1α), which reduces vascular endothelial growth factor a (VEGFA) expression, inhibiting cell proliferation." (PMID 39311117, 2024). "There is speculation that activation of the classical nuclear factor kappa B (NF-kB) pathway occurs in endometrial cancer cells through HIF-1α." (PMID 39337406, 2024). "It appears that the level of hypoxia-inducible factor 1-alpha (HIF-1α), which increases in the presence of cobalt chloride (II), may be associated with the aggressiveness of endometrial cancer." (PMID 39337406, 2024). "Our findings suggest that activation of NFAT5—HIF-1α—COX2 axis could promote endometrial cancer progression." (PMID 38612478, 2024). "The expression of hypoxia-inducible factor (HIF-1α), the concentration of which increases in the presence of cobalt (II) chloride, may correlate with endometrial cancer malignancy." (PMID 36611913, 2022). "This speculation was also supported by another study which suppression of the HIF1-α/VEGF pathway with NVP-BEZ235 or UO126 treatment resulted in the radiosensitization of endometrial cancer cells." (PMID 32403326, 2020). "In a study where immunohistochemical expressions of leptin, Ob-R and hypoxia-inducible factor-1α (HIF-1α) were analyzed in endometrial cancer tissue, immunoreactivity for leptin and Ob-R protein was observed in 56.7% and 30.0% of endometrial cancer cases, respectively." (PMID 30510663, 2018). "We explored expression patterns of the proposed hypoxia marker HIF-1α in endometrial cancer (EC) and investigate whether preoperative functional imaging parameters are associated with tumor hypoxia." (PMID 27634881, 2016). "Recent studies have suggested that DEC2 may regulate HIF-1α expression in human breast and endometrial cancers." (PMID 25884381, 2015). "To assess whether TM treatment suppresses the HIF signaling pathway in gynecologic cancer cells, we first determined the effects of TM on HIF-1α protein levels using immunoblotting in ECC-1 human endometrial cancer cells." (PMID 26469226, 2015). "DEC2 overexpression promotes HIF-1α degradation in breast and endometrial cancers." (PMID 25884381, 2015). "HIF-1α modulates angiogenesis not only in normal endometrium but also in endometrial cancer." (PMID 24745019, 2014). "Our study confirmed the expression of HIF-1α in endometrial cancer." (PMID 24745019, 2014). "Furthermore, the association between the expression of HIF-1α, increasing level of angiopoietin-1/angiopoietin-2, and enhanced synthesis of IL-8 was documented, also confirming the role of HIF-1α in the angiogenesis of endometrial cancer." (PMID 24745019, 2014). "Whether the different HIF-1α expression patterns have different prognostic implications in endometrial cancer is yet unknown." (PMID 20565904, 2010). "HIF-1α expression is correlated with a poor prognosis in endometrial cancer." (PMID 20169098, 2010). "Further studies are needed to show whether adaptation of therapy protocols might be of benefit for endometrial cancer patients with perinecrotic HIF-1α overexpression." (PMID 20565904, 2010). "Detectable levels of HIF-1α were found in all endometrial carcinomas." (PMID 20565904, 2010). "In conclusion, multimodal parameters by ESWAN and DCE-MRI were promise to serve as an important guide for quantitatively evaluating HIF-1α expression in endometrial cancer, which may help to predict the prognosis of the tumor and appropriately adjust the therapeutic regimen." (PMID 39723370, 2024). "Thus, diffuse nonhypoxia-related expression of HIF-1α seemed not to be related to PTEN mutation in endometrial cancer." (PMID 20169098, 2010). "This study aimed to examine the correlation between HIF-1α and GLUT-1 expression, tumor histologic grade, and clinicopathological features in patients with endometrial cancer." (PMID 39202223, 2024).
endometrial cancer (continued). "This study provides evidence for the intricate relationship between HIF-1α and GLUT-1 expression and the clinicopathological characteristics of endometrial cancer." (PMID 39202223, 2024). "Knocking out Hif1a or Hif1b in mouse-derived endometrial tumoroids partially recapitulated the effect of menin inhibition by MI-136 or genetic knockout on tumoroid growth, suggesting that menin may promote endometrial cancer growth through the activation of HIF target genes." (PMID 39336822, 2024). "This study aimed to evaluate HIF-1α and GLUT-1 expression in endometrial cancer and correlate their expression with clinicopathological features." (PMID 39202223, 2024). "In endometrial cancer cell lines, inhibition of the PI3K pathway has been shown to sensitize cancer cells to radiotherapy through downregulation of HIF-1α." (PMID 37644107, 2023). "A positive correlation between overexpression of leptin and hypoxia-inducible factor 1 alpha (HIF-1α), an indicator of tissue hypoxia consisting of two subunits, was clearly observed in endometrial cancer tissues." (PMID 36578551, 2022). "As shown in endometrial cancer cell lines, H19 is sponging miR-20b-5p which directly targets the 3′UTR of HIF-1α and thus inhibits HIF-1α expression." (PMID 32640630, 2020). "In in endometrial carcinoma cells, hypoxia can activate NF-κB pathway, resulting in the transactivation of HIF-1α gene, while HIF-1α can enhance NF-κB transcriptional activity." (PMID 28173803, 2017). "The aim of our study was to investigate the correlation between HIF-1α, GLUT-1, and CAIX protein level with the clinicopathological features of endometrial cancer patients." (PMID 24745019, 2014). "Our results indicate that also in endometrial cancer, the pattern of HIF-1α expression is more important for the prognosis than percentage and intensity of HIF-1α expressing cells in general." (PMID 20565904, 2010). "HIF-1α and VEGF are also closely related to early lymphatic metastasis of endometrial cancer." (PMID 30935077, 2019). "HIF1A, NF-kB and PI3K/mTOR might be potential treatment targets in aggressive endometrial cancers with presence of tumor necrosis." (PMID 26485755, 2015). "Considering the previous reports that DEC2 promoted HIF-1α degradation in breast and endometrial cancers, one would expect a negative correlation between DEC2 and HIF-1α." (PMID 25884381, 2015). "As indicated by our data, HIF1A, NF-kB and PI3K/mTOR might be potential targets in aggressive endometrial cancers with presence of tumor necrosis." (PMID 26485755, 2015). "The nuclear expression of HIF-1α was found in 97% cases, the cytoplasmic-membranous expression of GLUT-1 was found in 100% cases, and the cytoplasmic-membranous expression of CAIX was found in 89% cases of endometrial cancer." (PMID 24745019, 2014). "Interestingly, Karna and colleagues recently reported that BA inhibited the expression of HIF-1α and vascular endothelial growth factor (VEGF) in human endometrial cancer cells." (PMID 21731766, 2011). "Thus mutual relationships in the expression of both HIF1A and EPAS1 and VEGFA but also with other genes and proteins could be of importance also in endometrial cancer progression." (PMID 39888575, 2026). "In the endometrial cancer model, the level of MST2 cleavage correlates positively with HIF-1α expression, and MST inhibition attenuates HIF-1α-mediated transcriptional activity, suggesting that MST2 may indirectly influence Caspase-dependent apoptosis by modulating HIF-1α." (PMID 41256331, 2025). "In addition, larger, more comprehensive studies incorporating diverse histological types, adjuvant treatment modalities, molecular classification, and comorbidities are needed to fully understand the complex interplay between HIF-1α, GLUT-1, and other factors in endometrial cancer." (PMID 39202223, 2024).
endometrial cancer (continued). "We review our understanding of the role of HIF-1α/ERRα in promoting tumor growth adaptation and pyroptosis resistance, emphasize its key role in energy homeostasis, and explore the regulation of HIF-1α/ERRα in preventing and/or treating endometrial carcinoma patients." (PMID 35800058, 2022). "In endometrial cancer tissues, the lower the degree of differentiation and the later the stage, the stronger is the positive expression rate of HIF-1α and the positive correlation with VEGF expression, suggesting that HIF-1α promotes angiogenesis by the regulation of the target gene, VEGF." (PMID 30935077, 2019). "The aim of this study was to verify the usefulness of HIF-1α, GLUT-1, and CAIX, determined immunohistochemically in primary tumor and analyzed together with other clinical parameters, in predicting prognosis and planning tailored treatment of endometrial cancer patients." (PMID 24745019, 2014). "HIF-1α showed significantly higher expression in recurrent endometrial carcinomas when compared with their primary tumours; it was, however, not an independent predictor for recurrent endometrial carcinoma." (PMID 20169098, 2010). "The present study thus explored whether NFAT5 is expressed in human endometrial cancer tissue, whether NFAT5 expression in endometrial cancer cells is sensitive to HIF-1α, and investigated whether NFAT5 activation influences the expression of HIF-1α and COX2 signaling cascade in EnCa pathogenesis." (PMID 38612478, 2024). "Moreover, higher HIF-1α expression was found for nonendometrial compared to endometrial cancer." (PMID 24745019, 2014). "The link between estrogen-receptor-alpha (ERα), progesterone receptor (PR), hypoxia-inducible factor 1-alpha (HIF1-α), SLUG, and miR-221 circuit was also investigated in obese and nonobese women diagnosed with endometrial cancer, but further studies are needed in this regard." (PMID 34199293, 2021).
multiple myeloma (64 papers, 2011 to 2026). "Upregulation of B7-H4 has been reported in hypoxia-associated pathological situations in multiple myeloma cells, and overexpression of HIF-1α was associated with increased transcription of B7-H4." (PMID 35563753, 2022). "Hypoxia in the bone marrow causes myeloma cell upregulation of HIF1α which regulates secretion of proangiogenic cytokines." (PMID 33634031, 2020). "Additionally, a study has shown that the expression of HIF-1α in bone marrow endothelial cells is associated with disease relapse and drug resistance in multiple myeloma patients, and it represents a promising therapeutic target." (PMID 39757165, 2025). "HIF1α is also upregulated in circulating plasma cells and is associated with myeloma EMT." (PMID 33634031, 2020). "A novel study showed that TRIM44 stabilizes HIF-1α via deubiquitination and then promotes quiescent multiple myeloma cell occupancy and survival." (PMID 39757165, 2025). "Despite these findings, research on the role of HIF-1α in the context of cardio-oncology in multiple myeloma is limited." (PMID 39757165, 2025). "When stimulated with IL-6, HIF-1α and HLA-G in the myeloma cell lines were subjected to ubiquitination and degradation." (PMID 38877399, 2024). "The ubiquitinated HIF-1α and HLA-G proteins were identified in the three myeloma cell lines after 4-h treatment with IL-6." (PMID 38877399, 2024). "This is exemplified by decreased HIF1α levels after MYC knock-down in multiple myeloma cells, and stabilization of HIF1α proteins after MYC overexpression." (PMID 37601651, 2023). "We previously showed that hypoxia promotes IL-32 expression through HIF1α in multiple myeloma cells." (PMID 37313466, 2023). "HK2 has also been found to contribute to an anti-apoptotic effect in myeloma cells whilst in vivo studies have found increased efficacy of the chemotherapy agent melphalan in the presence of an inhibitor of HIF1α." (PMID 36320041, 2022). "In multiple myeloma, hypoxia-inducible factor-1α (HIF-1α) can bind to the B7-H4 promoter and induce B7-H4 expression." (PMID 35410218, 2022). "The expression of hypoxia-inducible factor (HIF)-1α was upregulated in myeloma cells under hypoxic conditions (2% O2 and 1% O2), and the upregulation of HIF-1α was more evident in myeloma cells cultured for 4 weeks compared with those cultured for 2 weeks." (PMID 33854583, 2021). "HIF-1α is highly expressed in myeloma bone marrow and is considered as a regulator of cellular metabolism." (PMID 34768861, 2021). "It seems that the aberrant activation of HIF-1α is a malignant feature of myeloma, and this further supports the growth of myeloma cells." (PMID 33420361, 2021). "Of interest, KDM3A restoration is the base to acquire an anti-apoptotic phenotype of myeloma cell apoptosis in chronic hypoxia through accumulating HIF-1α." (PMID 34044859, 2021). "The forced expression of HIF-1α directly upregulated MMSET expression in myeloma cells at the mRNA and protein levels." (PMID 33420361, 2021). "A study suggested that HIF-1α inhibition in myeloma cells can restrain tumor growth in vivo, which is accompanied by reduced angiogenesis and bone destruction." (PMID 33420361, 2021). "Taken together, our results demonstrated that hypoxia induces HIF-1α to promote MMSET expression in myeloma cells, ultimately contributing to the upregulation of DKK1." (PMID 33420361, 2021). "Myeloma cells are known to produce numerous angiogenic regulators including HIF1α and vascular endothelial growth factor (VEGF)." (PMID 34945712, 2021). "They found that knockout of H19 impaired the nuclear translocation of HIF-1α in multiple myeloma cell lines under hypoxic conditions, thereby inhibiting its capability as a transcription factor." (PMID 32640630, 2020). "In the presence of hypoxic conditions, myeloma cells upregulate hypoxia induced factor 1α (HIF1α), which regulates transcription of pro-angiogenic cytokines including HGF, bFGF, VEGF, and Angiopoietin-2 (Ang-2)." (PMID 33634031, 2020).